TRBV23-1 (T cell receptor beta variable 23-1 (non-functional))
Description:
Probable non-functional open reading frame (ORF) of V region of the variable domain of T cell receptor (TR) beta chain. Non-functional ORF generally cannot participate in the synthesis of a productive T cell receptor (TR) chain due to altered V-(D)-J or switch recombination and/or splicing site (at mRNA level) and/or conserved amino acid change (protein level). Alpha-beta T cell receptors are antigen specific receptors which are essential to the immune response and are present on the cell surface of T lymphocytes. Recognize peptide-major histocompatibility (MH) (pMH) complexes that are displayed by antigen presenting cells (APC), a prerequisite for efficient T cell adaptive immunity against pathogens. Binding of alpha-beta TR to pMH complex initiates TR-CD3 clustering on the cell surface and intracellular activation of LCK that phosphorylates the ITAM motifs of CD3G, CD3D, CD3E and CD247 enabling the recruitment of ZAP70. In turn ZAP70 phosphorylates LAT, which recruits numerous signaling molecules to form the LAT signalosome. The LAT signalosome propagates signal branching to three major signaling pathways, the calcium, the mitogen-activated protein kinase (MAPK) kinase and the nuclear factor NF-kappa-B (NF-kB) pathways, leading to the mobilization of transcription factors that are critical for gene expression and essential for T cell growth and differentiation. The T cell repertoire is generated in the thymus, by V-(D)-J rearrangement. This repertoire is then shaped by intrathymic selection events to generate a peripheral T cell pool of self-MH restricted, non-autoaggressive T cells. Post-thymic interaction of alpha-beta TR with the pMH complexes shapes TR structural and functional avidity.
Synonyms: TRBV231; TCRBV19S1P; TCRBV23S1
Gene: T-cell receptor variable (V) gene on chromosome 7 (142,645,961 to 142,646,467, forward strand). Ensembl gene ENSG00000211749.
Subcellular location: Cell membrane
Gene Ontology:
Biological process: cell surface receptor signaling pathway
Cellular component: plasma membrane
Homologues: Orthologues: macaque TRBV23-1 (91% identical), mouse Trbv26 (63% identical), mouse Trbv23 (57% identical). Paralogues in human: TRBV16 (54% identical), TRBV12-5 (44% identical), TRBV18 (44% identical), TRBV11-2 (43% identical), TRBV4-1 (43% identical), TRBV7-3 (43% identical), TRBV11-1 (42% identical), TRBV17 (42% identical), TRBV4-2 (42% identical), TRBV7-9 (42% identical), TRBV9 (42% identical), TRBV11-3 (41% identical), and 39 more.
Diseases named in the same sentence as TRBV23-1 in open-access papers:
TRBV23-1 is named in the same sentence as 1 disease in open-access papers, as found by Europe PMC text mining. Sharing a sentence is not in itself a finding about the gene and the disease.
TRBV23-1 shares sentences with these, for which no sentence is quoted: autoimmune disease (1 paper).